B3GNT8 (UDP-GlcNAc:betaGal beta-1,3-N-acetylglucosaminyltransferase 8)
Description:
Beta-1,3-N-acetylglucosaminyltransferase that functions in the elongation of specific branch structures of multiantennary N-glycans. Has strong activity towards tetraantennary N-glycans and 2,6 triantennary glycans.
Synonyms: Beta3Gn-T8; B3GALT7; BGALT15
Tractability: Antibody: UniProt predicts a signal peptide or a membrane-spanning region.
Gene: Protein-coding gene on chromosome 19 (41,425,359 to 41,428,730, reverse strand). Ensembl gene ENSG00000177191.
Subcellular location: Golgi apparatus membrane
Pathways (Reactome):
Metabolism of proteins: O-linked glycosylation of mucins
Gene Ontology:
Molecular function: N-acetyllactosaminide beta-1,3-N-acetylglucosaminyltransferase activity; protein binding; UDP-glycosyltransferase activity; hexosyltransferase activity
Biological process: poly-N-acetyllactosamine biosynthetic process; carbohydrate derivative metabolic process; glycoprotein biosynthetic process
Cellular component: extracellular exosome; Golgi membrane; membrane
Genetic constraint (gnomAD): Loss-of-function variants: 3 observed, 3.02 expected, observed/expected ratio (o/e) 0.99, 90% interval 0.43 to 1.86. That is too few expected variants to judge how well the gene tolerates losing a copy. Missense variants: 502 observed, 533.11 expected, observed/expected ratio (o/e) 0.94, 90% interval 0.87 to 1.01. Synonymous variants: 258 observed, 239.08 expected, observed/expected ratio (o/e) 1.08, 90% interval 0.97 to 1.2.
Homologues: Orthologues: chimpanzee B3GNT8 (99% identical), macaque B3GNT8 (97% identical), pig B3GNT8 (85% identical), dog B3GNT8 (84% identical), rabbit B3GNT8 (81% identical), guinea pig B3GNT8 (80% identical), rat B3gnt8 (76% identical), mouse B3gnt8 (76% identical), tropical clawed frog b3gnt6 (36% identical), zebrafish b3gnt2l (33% identical), Drosophila melanogaster brn (21% identical), Caenorhabditis elegans bre-5 (17% identical), and 2 more. Paralogues in human: B3GNT2 (31% identical), B3GNT6 (30% identical), B3GNT9 (29% identical), B3GNT4 (29% identical), B3GNT7 (28% identical), B3GNT3 (28% identical), B3GNT5 (22% identical), B3GALT4 (22% identical), B3GALT2 (21% identical), B3GALT9 (21% identical), B3GALT5 (20% identical), B3GALT6 (20% identical), and 3 more.
Diseases named in the same sentence as B3GNT8 in open-access papers:
B3GNT8 is named in the same sentence as 21 diseases in open-access papers, as found by Europe PMC text mining. Sharing a sentence is not in itself a finding about the gene and the disease. The quoted sentences say what the papers report.
embryonal carcinoma (2 papers, 2022 to 2025). A non-seminomatous malignant germ cell tumor characterized by the presence of large germ cells with abundant cytoplasm resembling epithelial cells, geographic necrosis, high mitotic activity, and pseudoglandular and pseudopapillary structures formation. "A recent analysis of the Cancer Genome Atlas demonstrated that KIT, KRAS, and NRAS gene variants were observed only in seminoma, while gene variants in B3GNT8, CAPN7, FAT4, GRK1, TACC2, and TRAM1L1 occurred only in embryonal carcinoma." (PMID 41426877, 2025). "Mutations in ADAMTS20, ARHGAP10, OR1L4, PDS5A, and RPLP0 were only found in mixed germ cell tumors, while mutations in B3GNT8, CAPN7, FAT4, GRK1, TACC2 and TRAM1L1 were only observed in embryonal carcinoma, and their mutation frequency was around 2%." (PMID 36713456, 2022). "Differences in somatic mutations between subtypes are also of concern, with our results suggesting that mutations in some genes (B3GNT8, CAPN7, FAT4, GRK1, TACC2, and TRAM1L1) occur only in embryonal carcinoma, while mutations in KIT, KARS, and NRAS are observed only in seminoma." (PMID 36713456, 2022).
colon cancer (1 paper, 2017). "Similarly, we found the beta‐1,3‐N‐acetylglucosaminyltransferase B3GNT8 to be upregulated (fold change = 3.46), in FUT9 knockdown cells, consistent with previous reports in colon cancer." (PMID 29196508, 2017).
Crohn disease (1 paper, 2025). A gastrointestinal disorder characterized by chronic inflammation involving all layers of the intestinal wall, noncaseating granulomas affecting the intestinal wall and regional lymph nodes, and transmural fibrosis. "Given this non-redundant function, our study reveals that B3GNT8 expression is significantly reduced in pediatric patients with Crohn's disease (CD) and ulcerative colitis (UC)." (PMID 41380967, 2025).
inflammatory bowel disease (1 paper, 2025). A spectrum of small and large bowel inflammatory diseases of unknown etiology. "In humans, both mRNA and protein levels of B3GNT8 significantly decrease in the intestinal mucosa of pediatric inflammatory bowel disease (IBD) patients." (PMID 41380967, 2025).
migraine (1 paper, 2023). "B3GNT8 is a key candidate gene for regulating migraine-associated gastrointestinal symptoms and hormonal modulation for migraine prevention." (PMID 37592229, 2023). "Given the higher prevalence of migraines in women and the influence of estrogen levels on migraine incidence, B3GNT8 emerges as a key candidate gene for the regulation of migraine-associated gastrointestinal symptoms.." (PMID 37592229, 2023). "Five genes, including ICA1L, TREX1, STAT6, UFL1, and B3GNT8, showed significant correlation with migraine in both the proteome and transcriptome." (PMID 37592229, 2023). "Furthermore, we integrated the plasma proteomic dataset with migraine GWAS data for another PWAS, identifying five more genes (MRVI1, PAPPA, B3GNT8, XCL2, and EPHA10) as potential risk genes." (PMID 37592229, 2023).
schizophrenia (1 paper, 2017). A major psychotic disorder characterized by abnormalities in the perception or expression of reality. "Recently, protein levels of important glycosylation enzymes, B3GNT8 and MGAT4A, were found decreased in the prefrontal cortex in schizophrenia (12 case–control pairs), whereas in our study B3GNT1, B3GNT3 and MGAT1 transcripts were downregulated in schizophrenia cases." (PMID 28418402, 2017).
cancer (3 papers, 2021 to 2023). A tumor composed of atypical neoplastic, often pleomorphic cells that invade other tissues. "Hence, B3GNT8, which is highly expressed in tumors but acts as a cancer inhibitor, is well worth further investigation." (PMID 38097951, 2023).
tumor (2 papers, 2023). "The Wilcoxon Rank Sum test revealed that ALG1L2, B3GNT3, and B3GNT8 were expressed at higher levels in tumor tissues, while HS6ST3 and ST8SIA5 were expressed at lower levels in tumor tissues (all P < 0.01)." (PMID 38097951, 2023).
infection (1 paper, 2020). The state of being infected such as from the introduction of a foreign agent such as serum, vaccine, antigenic substance or organism. "We observed that these genes did not change expression in non-CF ALI cultures upon infection with RV; ST8SIA4 (3.6-fold, p = 0.14); ST6GALNAC2 (−1.3-fold, p = 0.09); MAN1A1 (5.4-fold; p = 0.08); B3GNT8 (1-fold, p = 0.28)." (PMID 32765492, 2020).
B3GNT8 also shares sentences with these, for which no sentence is quoted: colorectal cancer (2 papers); seminoma (2); atherosclerosis (1); cervical cancer (1); colitis (1); gastric cancer (1); glioma (1); melanoma (1); mixed germ cell tumor (1); mucopolysaccharidoses (1); pancreatic cancer (1); ulcerative colitis (1).